HCN4 (hyperpolarization activated cyclic nucleotide gated potassium channel 4)
Diseases named in the same sentence as HCN4 in open-access papers (continued):
Sharing a sentence is not in itself a finding about the gene and the disease.
epilepsy (12 papers, 2018 to 2026). A brain disorder characterized by episodes of abnormally increased neuronal discharge resulting in transient episodes of sensory or motor neurological dysfunction, or psychic dysfunction. "To date, studies have reported HCN4 variants and abnormal expression implicated in epilepsy subtypes, including idiopathic generalized epilepsy and mTOR-related epileptic syndromes." (PMID 41603014, 2026). "In humans, HCN4 is expressed in the visual and nervous systems and has recently been associated with infantile epilepsy, suggesting that this patient’s undiagnosed disorder plausibly represents a phenotypic expansion of this gene." (PMID 40770127, 2025). "Genetic variants in the HCN1, HCN2, and HCN4 have been identified in patients with various forms of epilepsy, including febrile seizures, temporal lobe epilepsy, absence epilepsy, and epileptic encephalopathy." (PMID 39361439, 2024). "HCN channels are composed of four subunits (HCN1‐4), with HCN1, HCN2, and HCN4 previously linked to epilepsy." (PMID 39361439, 2024). "The role of HCN4 in the pathogenesis of epilepsy has been well established, as several pathogenic mutations have been identified; nevertheless, this kind of evidence is missing for the NP phenotype." (PMID 37893054, 2023). "Since the reported HCN4 cases had epilepsy and pathogenic variants with LOF effects, there is a need to investigate how LOF mutations can produce seizures." (PMID 35663267, 2022). "Pathogenic variants of HCN1, HCN2, HCN3, and HCN4 have been reported to be associated with epilepsy in 74 cases, and they have diverse phenotypes." (PMID 35663267, 2022). "The mutation V759I in HCN4 has been linked to cases of sudden unexpected death in epilepsy (SUDEP) and sudden infant death syndrome (SIDS)." (PMID 33095298, 2020). "The HCN4 mutation V759I had been previously classified as putatively pathogenic as it was found in cases of sudden unexpected death in epilepsy (SUDEP) and sudden infant death syndrome (SIDS)." (PMID 33095298, 2020). "Functional characterization in heterologous expression system and in neurons showed that the mutation determines a loss of function of HCN4 contribution to activity and an increase of neuronal discharge, potentially predisposing to epilepsy." (PMID 30127718, 2018). "HCN4 channels play a crucial role in regulating neuronal excitability, rhythmic firing, and synaptic transmission, and have been implicated as regulators of epilepsy susceptibility and network-level excitability." (PMID 41603014, 2026). "Furthermore, the evidence for variants in HCN1, HCN2, and HCN4 in human epilepsy has rapidly grown in recent years." (PMID 39361439, 2024). "Moreover, dysfunction in HCN channels, especially HCN1, HCN2, and HCN4 has been linked to multiple neurological and neurodegenerative disorders, including epilepsy, Alzheimer’s disease, Parkinson’s disease, and NP." (PMID 37893054, 2023). "We identified pathogenic variants of HCN1 (n = 24), HCN2 (n = 8), HCN3 (n = 2), and HCN4 (n = 6) that were associated with epilepsy in 74 cases (43 HCN1, 20 HCN2, 2 HCN3, and 9 HCN4)." (PMID 35663267, 2022). "Since the reported HCN4 cases had epilepsy and carried pathogenic variants with LOF effects, there is a need to investigate how LOF mutations produce seizures whereas the brain-specific HCN4-knockout adult mice exhibit reduced seizure susceptibility." (PMID 35663267, 2022). "In animal models, relevant studies have further support a role for abnormal HCN4 expression in epileptogenesis, indicating that HCN4 channels play a significant role in epilepsy and may represent a potential therapeutic target." (PMID 41603014, 2026). "Since HCN4 is highly expressed in cortical regions (including the hippocampus) specifically during infancy, and its expression rapidly declines with age, HCN4 deficit may represent a potential mechanism for infantile forms of epilepsy." (PMID 30127718, 2018).
epilepsy (continued). "Given that the abnormal expression of HCN4 in Rheb S16H mutant neurons is an mTORC1-dependent process (rapamycin treatment eliminated aberrant HCN4 expression) that can modulate epilepsy, it would be important to examine whether this phenotype is conserved across the different gene variants." (PMID 33897381, 2021). "Importantly, HCN4 expression in cortical regions is high at early stages of life and declines rapidly at later stages, suggesting a potential role of HCN4 dysfunctional behavior more specifically in infantile forms of epilepsy." (PMID 30127718, 2018). "Nevertheless, our data suggests that abnormal HCN4 channel expression is a conserved mechanism across these mTORC1-activating gene conditions and warrants further investigation of HCN-mediated excitability in mTORC1-related epilepsy." (PMID 38411613, 2024). "Interestingly, the blockage of HCN1-mediated Ih current in the pyramidal, cortical, and thalamic neurons contributes to epilepsy, whereas blockers of HCN3- and HCN4-mediated currents suppress seizures." (PMID 35663267, 2022). "Since HCN4 expression is high during infancy and declines with age, our data support the intriguing possibility that this HCN isoform has a more specific role in infantile forms of epilepsy." (PMID 30127718, 2018).
Brugada syndrome (9 papers, 2018 to 2025). A genetically heterogeneous condition characterized by complete or incomplete right bundle branch block accompanied by ST elevation in leads V1-V3. "The HCN4 gene is functionally close to SCN5A, and there is a known overlap between HCN4- and SCN5A-related conditions and suggestions on the possible modifying role of HCN4 in Brugada syndrome, which is also a SCN5A-related disease." (PMID 40299689, 2025). "More recently, a mutation located at the extracellular end of S6, identified in a Brugada syndrome patient, was found to shift the voltage dependence of the HCN4 channel by nearly 10 mV." (PMID 29936413, 2018).
atrioventricular block (8 papers, 2015 to 2024). A heart block that is initiated in the atrioventricular node. "However, a recent study also reported a novel HCN4 mutation, G1097W, which was associated with atrioventricular block." (PMID 27218255, 2016). "Knockout of an HCN channel (HCN4) in the mouse causes atrioventricular block." (PMID 26509807, 2015).
Ventricular arrhythmia (7 papers, 2013 to 2025). "HCN4 channels, one of the principal elements responsible for pacemaker currents, are associated with cardiac fetal reprogramming and supraventricular and ventricular arrhythmias, but their role in chagasic arrhythmias is not clear." (PMID 34835334, 2021). "These mice died of sudden arrhythmia aged eight weeks, indicating that HCN2 and HCN4 overexpression in the ventricles may contribute to ventricular arrhythmias." (PMID 26005035, 2015). "However they found inconsistent disruption of normal sinus rhythm on ECG and telemetry along with an unexplained increase in ventricular arrhythmias, possibly due to the undetected presence of HCN4 in conduction tissue in the ventricles." (PMID 24278453, 2013). "Although HCN4 expression is essential for proper SAN functioning, extreme activation of If in cardiac cells can lead to initiation of ectopic foci, resulting in atrial and ventricular arrhythmias." (PMID 33868385, 2021). "Furthermore the degree of HCN4 overexpression in a large group of explanted human failing hearts did not correlate with severity of ventricular arrhythmias or hear failure." (PMID 34682854, 2021).
cardiac hypertrophy (5 papers, 2018 to 2022). "In the present study, the selective upregulation of Hcn1 gene is consistent with previous studies using a mouse model of cardiac hypertrophy, although Hcn2 and Hcn4 are more abundant than Hcn150." (PMID 34489488, 2021). "In cardiac hypertrophy, expression of fetal type ion channels including HCN4 was reportedly reactivated in the ventricle." (PMID 29315578, 2018). "As a main result we found that AGAT−/− mice exhibited altered gene expression related to energy metabolism (Fbp2, Ucp2), cardiac hypertrophy and fibrosis (Nppa, Ctgf), immune response (Fgl2), and the conduction system of the heart (Dsc2, Ehd4, Hcn2, Hcn4, Scn4a, Scn4b)." (PMID 32179820, 2020).
channelopathies (5 papers, 2018 to 2022). "Channelopathies, such as mutations in the HCN4, SCN5A and KCNQ1 genes, which encode ion currents If, INa and IKs, can lead to reduced pacemaker rate." (PMID 34814734, 2021). "In addition, several other human HCN4 channelopathies have been reported that result in loss of HCN4 function." (PMID 34122140, 2021). "Moreover, several HCN4 channelopathies in humans (congenital diseases caused by mutations in genes coding for ion channels) lead to heterogeneous cardiac syndromes including bradycardia, yet in some of these channelopathies the response to β-adrenergic stimulation is preserved." (PMID 33144559, 2020). "Moreover, all patients with HCN4 channelopathies identified so far are heterozygous for the respective mutation and thus also express a “healthy” copy of the HCN4 channel." (PMID 33144559, 2020).
left ventricular noncompaction (4 papers, 2020 to 2025). Left ventricular noncompaction (LVNC) is a rare cardiomyopathy characterized anatomically by prominent left ventricular trabeculae and deep intratrabecular recesses causing progressive systolic and diastolic dysfunction, conduction abnormalities, and occasionally thromboembolic events. "It has also been reported that HCN4 is associated with left ventricular noncompaction cardiomyopathy (LVNC)." (PMID 40613349, 2025). "HCN4 mutations are implicated in familial sinus bradycardia, left ventricular noncompaction cardiomyopathy (LVNC), and TAD." (PMID 38370698, 2024).
sudden infant death syndrome (4 papers, 2015 to 2023). Unexpected death in infancy which remains unexplained following autopsy, review of the medical history, and investigation of the death circumstances and death scene. "This HCN4 variant was previously classified as putatively pathogenic because genetically linked to sudden infant death syndrome and malignant epilepsy." (PMID 33095298, 2020).
cardiomyopathy (3 papers, 2013 to 2025). A disease of the heart muscle or myocardium proper. "Half of the patients with HCN4 variant-causing SSS displayed the cardiomyopathy phenotype of LVNC." (PMID 40613349, 2025). "A previous study in the rat AVJ reported downregulation of HCN4 protein expression in ischaemic cardiomyopathy." (PMID 26509807, 2015).
ventricular tachycardia (3 papers, 2010 to 2022). A disorder characterized by an electrocardiographic finding of three or more consecutive complexes of ventricular origin with a rate greater than a certain threshold (100 or 120 beats per minute are commonly used). "Mutations of SCN5A, CACNA1C and CAV3 are associated with ventricular tachycardia, long-QT syndromes (LQT3,8,9), and sudden cardiac death while mutations of HCN4 cause sick sinus syndrome type 2." (PMID 20300641, 2010). "In this respect, we showed that atropine suppressed ventricular tachycardia in HCN4-AYA mice." (PMID 33144668, 2020).
Anxiety (2 papers, 2022 to 2023). Intense feelings of nervousness, tension, or panic often arise in response to interpersonal stresses. "In contrast, HCN4-KO showed significantly increased anxiety compared to controls." (PMID 37496803, 2023). "Interestingly, a dorsal hippocampus-specific knockdown of the HCN4 channel has also been reported to increase anxiety-like behavior in mice." (PMID 37496803, 2023). "Interestingly, the HCN4-KO has been shown to be reflected in thermal hypersensitivity and increased anxiety behavior, contrary to initial expectations based on the findings with HCN2-KO models." (PMID 37496803, 2023).
cardiac arrest (2 papers, 2017 to 2022). Cessation of breathing and/or cardiac function. "After deletion of HCN4 gene or one of the gene loci in adult mice, reduced amplitude of If current can be detected, and repeated cardiac arrest or bradycardia can be observed in surface electrocardiogram." (PMID 35788877, 2022).
Chronic Atrial and Intestinal Dysrhythmia Syndrome (2 papers, 2021 to 2023). "Here, the authors show that Shugoshin-1 controls cardiac pacemaker activity by interacting with HCN4 to enhance its cell-surface expression, and that the CAID-Syndrome mutation disrupts cardiac pacemaking by interfering with this important non-canonical interaction." (PMID 33953173, 2021). "Third, a substitution in the N-terminal domain of Sgo1 (K23E) disrupts its ability to directly interact with the pacemaker ion channel HCN4 in the membrane of cardiomyocytes of patients with Chronic Atrial and Intestinal Dysrhythmia Syndrome (CAID)." (PMID 38152060, 2023). "The clinical p.Lys23Glu mutation leads to an impairment in the interaction between Shugoshin-1 and HCN4, along with depressed funny-current and dysrhythmic activity in induced pluripotent stem cell derived cardiomyocytes derived from Chronic Atrial and Intestinal Dysrhythmia Syndrome patients." (PMID 33953173, 2021). "Our results confirmed that the non-canonical interaction between HCN4 and SGO1 is likely responsible for pacemaker dysfunction in CAID Syndrome." (PMID 33953173, 2021).
depression (2 papers, 2024). "The HCN4 gene, which is expressed in brain regions linked to mood and depression, has two SNPs (rs3859014 and rs12905212) significantly associated with major depression." (PMID 39529121, 2024). "Intriguingly, the role of HCN2 and HCN4 in major depressive disorder is less straightforward than HCN1." (PMID 39434909, 2024).
familial sick sinus syndrome (2 papers, 2010 to 2021). "Another possibility is that it is the result of a decline in the funny current, If, because blockade of If slows pacemaking and familial sick sinus syndrome has also been linked to mutations in HCN4 (main ion channel responsible for If); If and HCN4 are present in the SAN." (PMID 19729016, 2010).
generalized epilepsy (2 papers, 2018 to 2022). Epilepsy that is characterized by generalized seizure types and may have typical interictal and/or ictal EEG findings that accompany generalized seizure types (for example generalized spike-wave). "The patients carrying the HCN4 R550C mutation described here are affected by a mild form of infantile generalized epilepsy, with good response to pharmacological treatment, benign evolution and absence of sequelae in adulthood." (PMID 30127718, 2018). "A recent report has indicated the presence of HCN4 loss-of-function mutations in generalized epilepsy patients." (PMID 30127718, 2018). "For the HCN4 gene, most cases present with genetic or idiopathic generalized epilepsy." (PMID 35663267, 2022).
ischemia (2 papers, 2013 to 2020). A hypoperfusion of the BLOOD through an organ or tissue caused by a PATHOLOGIC CONSTRICTION or obstruction of its BLOOD VESSELS, or an absence of BLOOD CIRCULATION. "Thus, it could be worth investigating the role of other HCN family members, presumably HCN4, in the context of ischemia in future studies." (PMID 24373160, 2013).
mitral valve disease (2 papers, 2015 to 2023). "The ventricular non-compaction and mitral valve prolapse point to a role of HCN4 in the development of the myocardium and a role for dysfunctional HCN4 in structural abnormalities." (PMID 25642760, 2015).
myocardial infarction (2 papers, 2020 to 2021). Gross necrosis of the myocardium, as a result of interruption of the blood supply to the area, as in coronary thrombosis. "In previous studies, ivabradine administration counteracted the increase in ventricular HCN4 expression in post-myocardial infarction rats." (PMID 33897414, 2021). "In contrast, the same heart rate reducing HCN4 variant did not prevent a composite endpoint of myocardial infarction or cardiovascular death (OR 0.99, 95% CI: 0.93–1.04, P = 0.61)." (PMID 32692755, 2020). "There was no detectable association of the HCN4 heart rate-reducing variant with myocardial infarction or cardiovascular death in the cause-specific competing risk model." (PMID 32692755, 2020).
temporal lobe epilepsy (2 papers, 2019 to 2022). A localization-related (focal) form of epilepsy characterized by recurrent seizures that arise from foci within the temporal lobe, most commonly from its mesial aspect. "This is also supported by the evidence of the augmented HCN4 mRNA levels in the pilocarpine rodent model of temporal lobe epilepsy that relates to enlarged Ih in dentate granule cells." (PMID 35663267, 2022). "HCN4 mRNA levels are also increased in the pilocarpine rodent model of temporal lobe epilepsy, while in a cortical stroke model in which seizures develop, there is a switch from HCN2 to HCN4 channel expression in thalamocortical neurons." (PMID 31555092, 2019).
viral infections (2 papers, 2022 to 2026). "Additional expression of the pacemaker channel HCN4 further qualifies the differentiated cells as model system for viral infections in the human SAN." (PMID 35864219, 2022).
anorexia nervosa (1 paper, 2021). A disorder most often seen in adolescent females characterized by a refusal to maintain a minimally normal body weight, an intense fear of gaining weight, a disturbance in body image, and, in postmenarcheal females, the development of amenorrhea. "The purpose of this investigation was to examine heart rate variability (HRV), interbeat interval (IBI), and their interrelationship in healthy controls, bradycardic hyperpolarization‐activated cyclic nucleotide‐gated channel 4 (HCN4) mutation carriers, and patients with anorexia nervosa (AN)." (PMID 34322602, 2021).
atrial flutter (1 paper, 2022). A disorder characterized by an electrocardiographic finding of an organized, regular atrial rhythm with atrial rate of 240-340 beats per minute. "Our group published in a recent case study that variants in HCN4 can be associated with further prenatal arrhythmias-like atrial flutter." (PMID 36498454, 2022).
behavioural disorders (1 paper, 2018). "All strains of HCN4+/luc, HCN4+/tTA_TRE and HCN4Luc/tTA_TRE mice grew up normally without any apparent behavioural disorders." (PMID 29315578, 2018).
breast carcinoma (1 paper, 2020). "For example, the HCN4 gene is highly correlated with lower survival rates of breast cancer, and the gene PRB2 is significantly related to prognosis as an independent prognostic marker." (PMID 33537063, 2020). "HCN4 was highly correlated with lower survival rates of breast cancer." (PMID 33537063, 2020).
Chagas disease (1 paper, 2021). A parasitic infection caused by Trypanosoma cruzi. "Thus, we suggest, for the first time, that molecular remodeling by overexpression of HCN4 channels may be related to supraventricular arrhythmias in acute Chagas disease, causing ivabradine over-response." (PMID 34835334, 2021). "In conclusion, the present work showed, to the best of our knowledge for the first time, pharmacological and immunohistochemical evidence for HCN4 overexpression in auricles and ventricles in an EA mouse model of Chagas disease." (PMID 34835334, 2021). "As far as we know, this is the first report of HCN4 overexpression in Chagas disease." (PMID 34835334, 2021).
cocaine addiction (1 paper, 2024). "Cocaine addiction can increase the expression of HCN channels in prefrontal cortex, VTA, and other brain regions, while another study pointed out that the expression of HCN2 and HCN4 channels in VTA were downregulated after cocaine addiction." (PMID 39267158, 2024).
colon cancer (1 paper, 2019). "The SLC2A1 gene was related to the metabolic shift of colon cancer, and the HCN4 gene was correlated with low survival rate of multiple cancers." (PMID 31207989, 2019).